KCNH5 (potassium voltage-gated channel subfamily H member 5)
Description:
Pore-forming (alpha) subunit of a voltage-gated delayed rectifier potassium channel that mediates outward-rectifying potassium currents which, on depolarization, reaches a steady-state level and do not inactivate. The kinetic is characterized by a slow activation time course and a small voltage dependence of the activation time constants, therefore, starts to open at more negative voltages. The activation kinetics depend on the prepulse potential and external divalent cation concentration. The time course of activation is biphasic with a fast and a slowly activating current component. With negative prepulses, the current activation is delayed and slowed down several fold, whereas more positive prepulses speed up activation, therefore the activation rate depends on holding potential.
Synonyms: hEAG2; EAG2; Kv10.2; H-EAG2; DEE112
Tractability: Small molecule: an approved drug acts on it; it belongs to a druggable protein family. Antibody: its Gene Ontology location is reachable by antibodies, with high confidence; UniProt predicts a signal peptide or a membrane-spanning region. PROTAC: UniProt records ubiquitination sites on it; ubiquitination databases record sites on it.
Gene: Protein-coding gene on chromosome 14 (62,699,464 to 63,102,037, reverse strand). Ensembl gene ENSG00000140015.
Subcellular location: Membrane
Subcellular location (Human Protein Atlas): Centrosome; Cytosol; Nucleoplasm
Pathways (Reactome):
Neuronal System: Voltage gated Potassium channels
Gene Ontology:
Molecular function: delayed rectifier potassium channel activity; voltage-gated potassium channel activity; monoatomic ion channel activity; protein-containing complex binding; transmembrane transporter binding
Biological process: potassium ion transport; regulation of G2/M transition of mitotic cell cycle; potassium ion transmembrane transport; regulation of membrane potential; monoatomic ion transport; transmembrane transport
Cellular component: cell surface; voltage-gated potassium channel complex; plasma membrane; membrane
Genetic constraint (gnomAD): Loss-of-function variants: 36 observed, 85.62 expected, observed/expected ratio (o/e) 0.42, 90% interval 0.32 to 0.56. The upper end of that interval is the gene's LOEUF score, 0.56, which puts it in group 2 of 6, group 1 being the genes least tolerant of losing a copy. Missense variants: 836 observed, 1,189.4 expected, observed/expected ratio (o/e) 0.7, 90% interval 0.66 to 0.74. Synonymous variants: 405 observed, 437.55 expected, observed/expected ratio (o/e) 0.93, 90% interval 0.85 to 1.
Gene-disease validity (ClinGen):
ClinGen rates the evidence that KCNH5 causes each of these diseases.
infantile-onset epilepsy (autosomal dominant): Definitive. Epilepsy starting in the first 12 months of life, including self-limiting and refractory seizures, and epilepsies with and without developmental disorders.
Homologues: Orthologues: chimpanzee KCNH5 (99% identical), macaque KCNH5 (99% identical), pig KCNH5 (99% identical), dog KCNH5 (99% identical), rat Kcnh5 (98% identical), mouse Kcnh5 (98% identical), rabbit KCNH5 (98% identical), guinea pig KCNH5 (94% identical), tropical clawed frog kcnh5 (92% identical), zebrafish kcnh5a (80% identical), zebrafish kcnh5b (79% identical), Caenorhabditis elegans egl-2 (47% identical), and 2 more. Paralogues in human: KCNH1 (73% identical), KCNH7 (34% identical), KCNH2 (34% identical), KCNH8 (31% identical), KCNH6 (31% identical), KCNH3 (31% identical), KCNH4 (30% identical), HCN4 (18% identical), HCN1 (16% identical), HCN2 (16% identical), CNGA2 (15% identical), HCN3 (14% identical), and 5 more.
Diseases named in the same sentence as KCNH5 in open-access papers:
KCNH5 is named in the same sentence as 28 diseases in open-access papers, as found by Europe PMC text mining. Sharing a sentence is not in itself a finding about the gene and the disease. The quoted sentences say what the papers report.
medulloblastoma (10 papers, 2014 to 2024). A malignant, invasive embryonal neoplasm arising from the cerebellum. "KCNH5 is highly up-regulated in medulloblastomas, and targeted down-regulation of this channel reduced blastoma growth in vivo." (PMID 38527087, 2024). "The K+ channels EAG2 (KCNH5) and KCNT2 are highly expressed in the medulloblastoma of pediatric brain tumors." (PMID 38911514, 2024).
epilepsy (8 papers, 2022 to 2026). A brain disorder characterized by episodes of abnormally increased neuronal discharge resulting in transient episodes of sensory or motor neurological dysfunction, or psychic dysfunction. "Gain-of-function (GoF) mutations in KCNH1 (Kv10.1, hEAG1) and KCNH5 (Kv10.2, hEAG2) give rise to developmental disorders, intellectual disability, and epilepsy." (PMID 41656275, 2026). "In summary, the patients of KCNH5 mutation-related epilepsy presented with ASD or psychomotor development delay, except for the patient with the variant c.962G > A (p.S321N) of KCNH5 who presented with seizures without comorbidities." (PMID 35874597, 2022). "In epilepsy rats, upregulation of KCNH5 protein expression improved anxiety-like behavior and working memory." (PMID 35784838, 2022). "The genotype–phenotype correlation in KCNH5-related epilepsy has been reported several times." (PMID 39434833, 2024).
Epileptic encephalopathy (6 papers, 2015 to 2024). A condition in which epileptiform abnormalities are believed to contribute to the progressive disturbance in cerebral function. "Furthermore, 368 of 395 KCNH5 transcript variants found in ClinVar were reported as ‘Early infantile epileptic encephalopathy with suppression bursts’." (PMID 36068614, 2022). "The other overlaps with KCNH5—coding for a potassium channel that may be associated with epileptic encephalopathy." (PMID 34032215, 2021). "Diseases associated with KCNH5 mutations include early infantile epileptic encephalopathy (EIEE)." (PMID 34831225, 2021).
autism (5 papers, 2022 to 2024). Persistent deficits in social interaction and communication and interaction as well as a markedly restricted repertoire of activity and interest as well as repetitive patterns of behavior. "To date, only one disease-causing mutation of KCNH5 has been reported, and it involves a case that presented with seizures and autism symptoms." (PMID 35874597, 2022). "MG was also associated with SNPs in the brain- and neuron-specific genes, including cerebellum 4 precursor (CBLN4), potassium channel KCNH5, adenylate cyclase 8 (ADCY8), and autism susceptibility candidate gene AUTS2." (PMID 35711735, 2022). "There was a nominally significant set-level association with autism (P = 0.03) that would not remain significant if corrected for multiple testing over all language-related and psychiatric traits, with five genes individually associated at P < 0.05: BMPER, GATB, KCNH5, SNCA, and SYT2." (PMID 39133845, 2024).
Anxiety (3 papers, 2022). Intense feelings of nervousness, tension, or panic often arise in response to interpersonal stresses. "The results indicated that anxiety-like behavior in rats increased after the injection of lentiviral plasmids containing the coding sequence region of the KCNH5 gene (LV-KCNH5)." (PMID 35874597, 2022).
melanoma (3 papers, 2014 to 2022). A malignant, usually aggressive tumor composed of atypical, neoplastic melanocytes. "Therefore we propose that hypomethylation of the placental-specific KCNH5 promoter is frequently associated with KCNH5 expression in melanoma cells." (PMID 24759919, 2014). "Sequencing all samples from this PCR confirmed the use of the placental KCNH5 promoter in the 11 melanoma samples." (PMID 24759919, 2014). "Methylation and gene expression analysis revealed hypomethylation of this retrotransposon in melanoma cell lines, particularly in those samples that express the placental KCNH5 transcript." (PMID 24759919, 2014). "This study examined the promoter methylation and expression of the retrotransposon-derived KCNH5 transcript in 25 melanoma cell lines to determine whether the acquisition of ‘placental’ epigenetic marks is a feature of melanoma." (PMID 24759919, 2014). "KCNH5 expression was examined by RT-PCR to determine whether melanoma samples used the placental promoter for KCNH5 transcription." (PMID 24759919, 2014). "Given that the placental-specific transcript of KCNH5 has been detected in melanoma, we aimed to investigate whether its retrotransposon-derived promoter, which is hypermethylated in those studied normal tissues from the body, becomes hypomethylated in melanoma." (PMID 24759919, 2014). "Previous work investigating the oncogenic potential of a closely related EAG potassium channel (EAG1/KCNH1; ∼70% homologous to KCNH5) detected expression in several somatic cancer cell lines (including melanoma), normal adult brain and placenta, but not in other normal somatic cells." (PMID 24759919, 2014). "Thus the finding that melanoma samples express the placental transcript of KCNH5 is notable given that healthy (non-cancerous) melanocytes do not express either transcript of this gene." (PMID 24759919, 2014).
infantile spasms (2 papers, 2022 to 2023). A rare epilepsy syndrome characterized by onset of epileptic spasms in infants between 2 and 12 months of age, and rarely up to 24 months. "The patient with the variant c.2020-4A > G (splicing) of KCNH5 was diagnosed with West syndrome." (PMID 35874597, 2022).
blood disease (1 paper, 2021). A disease that occurs in the blood. "The top candidates include TNFAIP3, which has been reported before, but also include other, novel regions, containing genes involved in blood diseases (CYCS), neurological diseases (PRKCH, KCNH5, LRNN1), metabolism (SFRP4, SUMF1), and skin development (ASCL4, RAB27A)." (PMID 34032215, 2021).
glioma (1 paper, 2024). A benign or malignant brain and spinal cord tumor that arises from glial cells (astrocytes, oligodendrocytes, ependymal cells). "KCNH5 is widely expressed in the human brain, and mutations in this gene contribute to abnormal brain development, potentially playing a role in glioma development." (PMID 38584840, 2024).
tumor (13 papers, 2011 to 2025). "These genes, such as RFC1, XPO4, THEGL, SLC19A3, TBC1D4, and KCNH5, may have specific functions in metastatic tumour cells." (PMID 34507604, 2021). "However, KCNH5 expression and the other four proteins are affected by methylation of their coding gene sequences, and this mechanism seems to be affected by CBD, with implications in tumor development such as cell proliferation, resistance to apoptosis, angiogenesis, invasion, and metastasis." (PMID 40429863, 2025).
cancer (6 papers, 2011 to 2022). A tumor composed of atypical neoplastic, often pleomorphic cells that invade other tissues. "Although the function of KCNH1 is better understood than that of KCNH5, both of these genes are thought to be involved in cell cycle regulation and tumour progression in cancer." (PMID 24759919, 2014).
neurological diseases (2 papers, 2021 to 2022). "Our results also further support suggestions that the chromosomal region around 14q23.2, where KCNH5 is localised, might be a 'hot spot' for neurological diseases." (PMID 36068614, 2022).
central nervous system diseases (1 paper, 2022). "In central nervous system diseases, the pathogenicity of a variant of KCNH5 is poorly understood." (PMID 35874597, 2022).
KCNH5 also shares sentences with these, for which no sentence is quoted: autism spectrum disorder (2 papers); glioblastoma (2); intellectual disabilities (2); blastoma (1); brain tumors (1); cholera (1); dyslexia (1); hyperekplexia (1); neurodevelopmental disorder (1); pancreatic cancer (1); primary biliary cholangitis (1); renal cell carcinoma (1); status epilepticus (1); syndromic epilepsy (1); temporal lobe epilepsy (1).